MTOR (mechanistic target of rapamycin kinase)
Diseases named in the same sentence as MTOR in open-access papers (continued):
Sharing a sentence is not in itself a finding about the gene and the disease.
hepatocellular carcinoma (continued). "Research has shown that upregulation of PTTG1 expression promotes transcriptional activation of asparagine synthetase (ASNS), a key activator of Asn metabolism, enhancing Asn metabolism and activating mTOR pathway to promote progression of hepatocellular carcinoma." (PMID 40028341, 2025). "This pathway has been identified as a key factor in the development of hepatocellular carcinoma and is regulated by several miRNAs, including miR‐99a, miR‐100, and miR‐149, which inhibit mTOR, as well as miR‐9, miR‐30, miR‐125, miR‐149, and miR‐379, which inhibit AKT." (PMID 40754657, 2025). "It has been reported that SNRPD1 could be an oncogene that affects the development of hepatocellular carcinoma by controlling the mTOR pathway and autophagy." (PMID 38645487, 2024). "Moreover, STX5 has been recently described to modulate PI3K/mTOR pathway activation, subsequently restraining cell adhesion and thus favoring metastasis in hepatocellular carcinoma." (PMID 38564289, 2024). "Similarly, the sixfold induced alpha fetoprotein expression likely contributed to PTEN inhibition and, therefore, stimulated PI3K/Akt/mTOR signaling as shown for human hepatoma cell lines." (PMID 38245882, 2024). "AR upregulates integrin β1 expression through the PI3K/AKT/mTOR signal pathway, consequently, increasing in cellular adhesion, which could be a potential characteristic of advanced hepatocellular cancer with high metastasis." (PMID 38966543, 2024). "Notably, mTOR is commonly activated in hepatocellular carcinoma, which can progress from chronic hepatitis B. This review systematically summarizes the role of mTOR in the life cycle of HBV and its impact on the clinical progression of HBV infection." (PMID 39247820, 2024). "In summary, G-CSF can activate the PI3K/AKT/mTOR signaling pathway by inhibiting SHP2 activation in tumor-associated macrophages, and promoting the proliferation, migration, and angiogenesis of hepatocellular carcinoma cells, leading to the progression of hepatocellular carcinoma." (PMID 38967628, 2024). "In past studies, HSP90AA1 expression also favoured chemoresistance in osteosarcoma and distant metastasis in hepatocellular carcinoma by a mechanism that may be connected to PI3K/Akt/mTOR signaling and epithelial mesenchymal transition." (PMID 38263419, 2024). "In a cancer-specific manner, EEF1A2 has been reported to promote specific pathways, for example, TGF-β/SMAD signaling in lung adenocarcinoma, the PI3K/AKT/mTOR pathway in hepatocellular carcinoma, the ERK pathway in breast cancer, and PI3K signaling in brain cancer." (PMID 38172654, 2024). "Moreover, brusatol has been shown to reduce cell survival and promote cell death in hepatocellular carcinoma through autophagy via the PI3K/Akt/mTOR pathway." (PMID 39066290, 2024). "Furthermore, isoquercitrin is observed to induce autophagy in hepatocellular carcinoma cells through the activation of the AMPK/mTOR/p70S6K signaling pathway." (PMID 38535468, 2024). "Furthermore, the pro-apoptotic impact of Saikosaponin-D on hepatoma cells induced by radiotherapy was notably reversed after treatment with chloroquine or an mTOR agonist." (PMID 37834333, 2023). "It has been shown that Fn may promote CRC metastasis by activating the autophagic pathway, and H2S may promote autophagy in hepatocellular carcinoma cells by inhibiting the PI3K/Akt/mTOR signaling pathway." (PMID 37889013, 2023).
hepatocellular carcinoma (continued). "We speculate that S100A10 and ANXA2 may also activate the Akt/mTOR pathway in hepatocellular carcinoma." (PMID 37420211, 2023). "In addition, cucurbitacin I treatment results in the downregulation of MAPK, mTOR, and Akt expression in hepatocellular carcinoma." (PMID 37958903, 2023). "In another study performed in the HepG2 hepatoma cell line, hexanoic acid promoted basal and insulin-induced phosphorylation of the Akt-mTOR axis, maintaining a balance of lipid metabolism and potentially constituting an effective tool to manage liver steatosis and hepatic insulin resistance." (PMID 38027127, 2023). "In summary, our study reveals that the SREBP2 inhibitor betulin sensitizes hepatocellular carcinoma to lenvatinib by inhibiting the mTOR/IL-1β pathway, which may be a promising therapeutic strategy for patients with HCC." (PMID 37434430, 2023). "Indeed, such a connection between Sorafenib and the mTOR pathway has also been observed in hepatocellular carcinoma where treatment with Sorafenib in patients with increased PI3K/mTOR pathway activity results in reduced relapse rates." (PMID 36599821, 2023). "MELK regulated the AKT/mTOR signaling pathway, causing changes in the levels of GPX4, GSH, FTH1, xCT, heme oxygenase 1(HO-1), reactive oxygen species, and Fe2+ to regulate the ferroptosis of hepatoma cells." (PMID 37008632, 2023). "Additionally, the E2F1/DDX11 axis is capable of promoting malignant behaviors of hepatocellular carcinoma cells via activation of the PI3K/AKT/mTOR signaling pathway." (PMID 36777627, 2023). "Additionally, mTOR inhibitors can be used in patients transplanted for hepatocellular carcinoma, since they have been shown to have antiproliferative effects." (PMID 38993848, 2023). "In hepatocellular cancer, SNRPDI has been linked to overexpression in the mTOR pathway." (PMID 38132437, 2023). "Hence, dual blockade of SHP2 and mTOR can effectively suppress the mTOR pathway and drive anti‐cancer response, both in vitro and in vivo, in several hepatocellular carcinoma models." (PMID 36650715, 2023). "Blocking the overactivated PI3K/AKT/mTOR signaling pathway may be a potential target of B. coagulans MZY531 in treating hepatocellular carcinoma because it regulates cell growth and proliferation." (PMID 37705007, 2023). "It is quite a coincidence that circRPN2 could bind to ENO1 and accelerates its degradation to promote glycolytic reprogramming through the AKT/mTOR pathway, thereby inhibiting hepatocellular carcinoma (HCC) proliferation and metastasis." (PMID 36072431, 2022). "Severe interstitial injury was present in six patients, five of whom were receiving a CNI-based immunosuppression protocol, while the other one was receiving mTOR inhibitor only (CNI treatment had been discontinued six months before renal biopsy due to hepatocellular carcinoma relapse)." (PMID 36180855, 2022). "NAP1L5 inhibits the PI3K/AKT/mTOR signaling pathway in hepatocellular carcinoma by regulating MYH9." (PMID 36374212, 2022). "In addition, the migration of hepatocellular carcinoma cells was found to be impeded by the circ_0003645/miR-1299/PI3K/mTOR pathway." (PMID 35383130, 2022). "In addition, metformin up-regulated the ratio of LC3BII/I and induced autophagy via AMPK/mTOR signaling pathway in hepatocellular carcinoma." (PMID 36387221, 2022). "Notably, lncRNA MALAT1 regulates the mTOR pathway in various tissues and tumors, especially in hepatocellular carcinoma (HCC)." (PMID 35557985, 2022). "Mechanistically, we further demonstrated that celecoxib abrogated the activation of Akt/mTOR signalling in insulin‐stimulated hepatoma cells, followed by the reduction of downstream lipogenic proteins at the post‐transcriptional level in chronically insulin‐treated cohorts." (PMID 35713152, 2022).
hepatocellular carcinoma (continued). "Moreover, both rapamycin and NaHS notably suppressed the protein expression of p-PI3K, p-Akt, and mTOR in hepatoma cells, suggesting that H2S promoted autophagy through the PI3K/AKT/mTOR signaling pathway inhibition." (PMID 35409395, 2022). "Our group previously reported that suppressed ketone body production resulted from deranged tyrosine catabolism activated mTOR signaling and promoted early hepatic tumorigenesis, indicating an anti-tumor effect of ketone bodies in hepatocellular carcinoma (HCC)." (PMID 36358763, 2022). "In addition, AB4 treatment simultaneously induced apoptosis and autophagy through PI3K/Akt/mTOR signaling in hepatocellular carcinoma (HCC) cells." (PMID 35606807, 2022). "In addition, BCKDK promoted tumor growth and metastasis by interacting with SRC or mTOR in colon cancer or hepatic carcinoma." (PMID 35498541, 2022). "In addition, B7-H4 facilitates the proliferation and metastasis of colorectal carcinoma cell through PI3K/Akt/mTOR signaling pathway, as well as in large B-cell lymphoma and hepatocellular carcinoma." (PMID 34818980, 2022). "The PI3K/mTOR/AKT signal pathway of autophagy was activated by SHS-treated hepatoma cells." (PMID 36081558, 2022). "In addition, we found that the promoting effect of SSd on apoptosis in hepatoma cells induced by radiotherapy was significantly reversed after the addition of chloroquine or the mTOR agonist." (PMID 33628104, 2021). "In addition, regulatory role of miR-199a from adipose tissue-derived MSCs has also been reported to enhance the chemosensitivity in hepatocellular carcinoma through mTOR pathway." (PMID 33391511, 2021). "Myristicin exerts an efficient therapeutic effect on hepatic carcinoma by suppressing PI3K/Akt/mTOR signalling pathway; thus, it may be used as a new potential drug for hepatic carcinoma treatment." (PMID 34410900, 2021). "Moreover, novel lncRNA SFTA1P promotes tumor growth by downregulating miR-4766-5p via the PI3K/AKT/mTOR signaling pathway in hepatocellular carcinoma." (PMID 33995377, 2021). "Huanglian Jiedu decoction (HLJDD), a traditional Chinese Medicinal (TCM), could activate AMPK signaling and further inhibit the mTOR pathway, thus reducing the phosphorylation of eEF2K in hepatocellular carcinoma (HCC) cells." (PMID 33673713, 2021). "Change in the concentration of extracellular ATP from 1 mM to 2.5 mM tipped the balance from mechanistic target of rapamycin (mTOR)-mediated autophagy required for cell survival to AMP-activated kinase (AMPK)-mediated apoptosis-induced cell death in hepatoma cells." (PMID 34456873, 2021). "Notably, ropivacaine was found to suppress cell growth and survival in chronic myeloid leukemia by reducing the PI3K/AKT/mTOR pathway, and ropivacaine stimulates apoptosis of hepatocellular carcinoma by mediating Akt activity and caspase 3 cleavage." (PMID 34696683, 2021). "Our study demonstrated that ropivacaine was capable of inhibiting cell viability and enhancing apoptosis in HepG2 cells, and the potential anticancer mechanism of ropivacaine in hepatocellular carcinoma may involve the IGF-1 R/PI3K/AKT/mTOR axis." (PMID 34696683, 2021). "Similarly, in an intraperitoneal injection model of Yoshida AH-130 ascites hepatoma cells in Wistar rats, HMB was again found to reduce cachexia, and this observation was associated with mTOR activation." (PMID 34944981, 2021). "However, progranulin function in hepatocellular carcinoma is mediated through the mTOR pathway, and in cholangiocarcinoma, it involves the IL-6/progranulin/Akt axis." (PMID 34681875, 2021). "Besides being ubiquitously expressed in all eukaryotic cell types, mTOR is found to be upregulated in various cancers such as ovarian cancer, human hepatocellular carcinoma and cutaneous melanoma." (PMID 32326380, 2020).
hepatocellular carcinoma (continued). "Interestingly, de novo expression of LSEC FABP4 in response to exposure to glucose, insulin or hypoxia potentiates the oncogenic effects of hepatoma cell lines (HepG2, SKHep1, and Huh7) through activation of mechanistic target of rapamycin (mTOR) pathway." (PMID 33198153, 2020). "To date, several studies have shown that TIPE1 can inhibit the activation of Rac1, its downstream target p65, and the c-Jun N-terminal kinase pathway in hepatocellular carcinoma cells and decrease mTOR phosphorylation by stabilizing TSC2 protein in a Parkinson's disease model." (PMID 31179241, 2019). "Furthermore, it has been reported that lycorine promoted autophagy and apoptosis via TCRP1/Akt/mTOR axis inactivation in human hepatocellular carcinoma." (PMID 31263414, 2019). "However, the addition of the autophagy inhibitor chloroquine or mTOR agonist can partially reverse the inhibitory effect of the combined treatment of SSd with radiation on the proliferation of hepatoma cells." (PMID 31598167, 2019). "The mTOR pathway is activated in about 50% of patients with hepatocellular carcinoma (HCC)." (PMID 29899840, 2018). "Our previous study showed that N. nomurai venom (NnV) induces apoptotic cell death via dual inhibition of the phosphatidylinositol 3-kinase (PI3K)/Akt and mammalian target of rapamycin (mTOR) pathways in HepG2 human hepatocellular carcinoma cells and in a nude mouse model." (PMID 29434219, 2018). "Furthermore, arenobufagin (a bufadienolide from toad venom) suppressed the growth of HCC cells by inducing the initiation of autophagy in human hepatocellular carcinoma cells through inhibition of PI3K/AKT/mTOR pathway." (PMID 28915706, 2017). "We have shown previously that rapamycin, the canonical inhibitor of the mechanistic target of rapamycin (mTOR) complex 1, markedly inhibits the growth of focal lesions in the resistant hepatocyte (Solt-Farber) model of hepatocellular carcinoma (HCC) in the rat." (PMID 28199961, 2017). "PI3K/Akt/mTOR also participates in the process of hepatocellular carcinoma." (PMID 28659990, 2017). "7-KC activates PI3K/mTOR pathway to induce p-glycoprotein expression in Huh7 hepatoma cells." (PMID 27740938, 2016). "Moreover, metformin has been reported to inhibit EMT in lung adenocarcinoma, hepatocellular carcinoma, and inhibit mTOR signaling." (PMID 27916907, 2016). "When we inhibited mTOR in human hepatocellular carcinoma (HCC) and renal cell carcinoma (RCC) cells, using pharmacologic inhibitors or by RNA interference, we noticed shuttle of the glycolytic flux to gluconeogenesis pathway along with reduction in cellular proliferation and survival." (PMID 27551450, 2015). "In addition, FVII/PAR2 signaling elicits an mTOR-independent signaling, which promotes hepatoma cell migration in consistent with the clinical observations." (PMID 27551480, 2015). "Reduced AFP in the AFP-siRNA transfected, ChIP results indicated that human hepatoma PLC/PRF/5 cells were transfected with AFP-siRNA vectors led to an apparent reduction of binding of p-mTOR(Ser2448) to the promoter elements in the 5′-flanking region of the CXCR4 gene compared to the input." (PMID 25815363, 2015). "Downregulation of miRNAs were noted in some cancers, such as hepatocellular carcinomas, suggesting that tactics to regulate mTOR by elevating levels of miRNAs may be alternative therapeutic strategies for the treatment of cancer." (PMID 23434669, 2013). "It was demonstrated that mTOR pathway upregulated glycolysis in hepatocellular carcinoma." (PMID 23762265, 2013). "FLCs also show overexpression of the EGFR and the mTOR pathways, both pathways which are also commonly over-expressed in typically hepatocellular carcinomas and may have therapeutic possibilities." (PMID 24278737, 2012). "The mTOR pathway is dysregulated in 40–50% of human hepatocellular carcinomas." (PMID 19816606, 2009).
hepatocellular carcinoma (continued). "Collectively, these findings support the therapeutic potential of C. amuricus as a targeted agent for hepatocellular carcinoma (HCC) via modulation of the PI3K/AKT/mTOR signaling axis." (PMID 41511947, 2026). "Therefore, we hypothesized that MELK promotes PI3K/Akt/mTOR signaling by enhancing the protein stability of FABP5 in hepatoma cells." (PMID 39871325, 2025). "For example, in hepatocellular carcinoma (HCC), p62 supports carcinogenesis through activation of Nrf2, in papillary thyroid cancer through mTOR activation or in lung adenocarcinomas through NF-κB activation." (PMID 40593496, 2025). "Besides, these genes play a role in several significant KEGG pathways, including the Wnt signaling pathway, pathways of neurodegeneration−multiple diseases, transcriptional misregulation in cancer, hepatocellular carcinoma and mTOR signaling pathway, which are closely tied to cancer." (PMID 39980564, 2025). "In hepatocellular carcinoma (HCC), multiple mutations and dysregulated signaling pathways, including WNT, MAPK, mTOR, TGF-β, STAT, and TERT, drive tumor initiation and progression." (PMID 40563418, 2025). "Additionally, SOS Ras/Rac Guanine Nucleotide Exchange Factor 1 (SOS1) may induce EMT through the PI3K/Akt/mTOR pathway, thereby enhancing the invasion, migration, and metastasis of hepatocellular carcinoma cells." (PMID 40387965, 2025). "In hepatocellular carcinoma, the PI3K pathway often undergoes aberrant activation due to PI3K gene mutations or irregularities in factors upstream of the pathway, precipitating the activation of AKT and mTOR which, in turn, stimulate growth, proliferation, and dissemination of neoplastic cells." (PMID 38967628, 2024). "Treatment also downregulated the PI3 K/Akt, NF-κB, and mammalian target of rapamycin (mTOR) signaling pathways, as well as the migration and invasion of hepatocellular carcinoma (HCC) cells." (PMID 39335164, 2024). "Additionally, it has been found miR-199a/b-3p can inhibit HCC growth, apoptosis, invasion and angiogenesis via multiple targets, such as PDCD4, CD44, CD151, VEGFA AEGFR1/2, HGF and MMP235–38 and can affect the chemical sensitivity of hepatoma cells to doxorubicin via mTOR and c-Met39." (PMID 38168113, 2024). "In hepatocellular carcinoma (HCC), NMN supplementation notably enhanced the p-AMPK/AMPK ratio, which in turn promotes autophagy and ferroptosis via activating the AMPK/mTOR signaling pathway, thereby contributing to the suppression of HCC progression." (PMID 39408861, 2024). "Moreover, function enrichment analysis revealed that transitional cells specifically activated signalling pathways including NOD‐like receptor signalling, PI3K‐AKT signalling, mTOR signalling, Hedgehog signalling, hepatocellular carcinoma, and non‐alcoholic fatty liver disease pathways." (PMID 37994257, 2024). "There is limited published information regarding the expression of mechanistic target of rapamycin (mTOR) in vessels that encapsulate tumor cluster (VETC)‐positive hepatocellular carcinoma (HCC)." (PMID 38250695, 2024). "The PI3K/AKT/mTOR signaling pathway is recognized as a critical driver of hepatocellular carcinoma (HCC) activation." (PMID 39459028, 2024). "Considering the dual role of autophagy in hepatocellular carcinoma (HCC), the importance of sustaining balanced autophagy activity within the PI3K/AKT/mTOR pathway to enable statins to stimulate autophagy in HCC." (PMID 37894467, 2023). "The expression level of mTOR (mammalian target of rapamycin) is high in hepatocellular carcinoma (HCC) and its pharmacological inhibition can reduce tumor cell proliferation." (PMID 37630248, 2023). "Moreover, cancer patients with high expression of GSTA1-1 in their tumors had better prognoses, and the isoenzyme may serve a protective role against hepatocellular carcinoma by suppressing the AMPK/mTOR-signaling pathway." (PMID 37189435, 2023).